IL6 (interleukin 6)
Diseases named in the same sentence as IL6 in open-access papers (continued):
Sharing a sentence is not in itself a finding about the gene and the disease.
viral infection (continued). "Mechanistically, the protective allele disrupted the CTCF-binding locus at the IL-6 intron and resulted in attenuated IL-6 induction in response to viral infection." (PMID 36204639, 2022). "The immune-mediated tissue pathology during viral infection is fueled by pro-inflammatory cytokines such as IL-6, TNF-α and IL-1β." (PMID 35512020, 2022). "IL-6 (cut-off value: 2 pg/ml) was shown to be the most sensitive biomarker when distinguishing bacterial from viral infections with sensitivity of 68% and specificity of 69%." (PMID 35582414, 2022). "The N protein of SARS-CoV-2 was reported to promote inflammation by increasing IL-6 levels following virus infection." (PMID 34716845, 2022). "In vitro and clinical studies show that IL-27 can interact with IL-6 to form a complex during viral infection." (PMID 35634328, 2022). "Such an effect on iron homeostasis can be related to the ability of Lf to chelate free iron and downregulate pro-inflammatory cytokines, such as IL-1β and IL-6, thus boosting anti-oxidant and anti-inflammatory host response to viral infection." (PMID 36297546, 2022). "The STAT1 protein can be activated by molecules such as interferon-α, EGF, and IL6 and participate in the immune response to viral infection." (PMID 35928229, 2022). "While several studies show the essential role of IL-6 to mount a proper immune response during some viral infections, others link this cytokine with exacerbation of viral diseases." (PMID 35463639, 2022). "Numerous studies have demonstrated that acute viral infections can induce M1 macrophage polarization, which results in the release of pro-inflammatory factors, such as IL-1β, IL-6, and iNOS." (PMID 36147321, 2022). "The activation of NF-κB in viral infection induces gene expression of a wide range of cytokines (e.g., IL-1, IL-2, IL-6, IL-12, TNF-α, LT-α, LT-β, and GM-CSF), and chemokines (e.g., IL-8, MIP-1, MCP1, RANTES, and eotaxin)." (PMID 35967323, 2022). "Co-infection with a non-mucoid PA isolate increased IL-1β protein concentrations (28.88 pg/ml vs. 6.10 pg/ml), but in contrast drastically diminished levels of IL-6 protein (53.17 pg/ml vs. 2301.33 pg/ml) compared to virus infection alone." (PMID 35265536, 2022). "Both IL-6 and IL-1β are major proinflammatory cytokines released during viral infections to induce acute-phase protein secretion by hepatocytes which activate the complement system." (PMID 35464491, 2022). "IL-6 mediates cellular and humoral immune responses; therefore, adequate cytokine levels are crucial for determining the outcome of viral infection." (PMID 35336914, 2022). "We also envision other bacterial infection-specific biomarkers, such as interleukin-6 (IL-6), can be incorporated into our multiplexed LFA platform to further increase the diagnostic accuracy for differentiating bacterial and viral infections." (PMID 35149284, 2022). "During viral infection, virus-induced inflammation leads to systemic or local production of cytokines, such as interleukin-6 (IL-6), tumor necrosis factor-α (TNF-α), interferon (IFN) and monocyte chemoattractant protein 1 (MCP-1)." (PMID 36303865, 2022). "The role of IL-6 as a biomarker in neuroinflammatory CNS diseases has been extensively evaluated, but the data on CNS viral infections are more limited." (PMID 36366333, 2022). "Meanwhile, the activation of IFITM2 and IL-6 forms a reciprocally positive feedback loop to make MM malignant progenitor cells act out the expression pattern with virus infection." (PMID 36131282, 2022). "During viral infection, two principal mechanisms occur to modulate ferritin levels, iron availability, and inflammatory cytokines levels: IL-1β and IL-6." (PMID 36613462, 2022). "Virus infection stimulated the production of inflammatory and antiviral mediators, including interleukin (IL)-6, CXCL-8, tumor necrosis factor (TNF)-α, and type I/III interferons." (PMID 35265536, 2022).
viral infection (continued). "The pro-inflammatory IL-6 is the major cellular factor produced after cell damage induced by viral infection." (PMID 35746745, 2022). "IHNV invasion also resulted in significant upregulation in the expression of il6, which has been shown to be essential for inflammatory resolution and migration and phagocytic activities of macrophages in mammals during viral infections." (PMID 36430516, 2022). "As a stable indicator, changes in IL-6 levels can indicate inflammatory conditions during a viral infection." (PMID 35336861, 2022). "Harker and colleagues showed that the induction of IL-6 in late phases of chronic viral infection drive Tfh cell generation and germinal centre responses, which is also mediated through IL-6 trans-signalling." (PMID 35619117, 2022). "We also detected the inflammatory cytokines including IL-6 and TNF-α which play important roles in viral infection caused tissue damage and cytokine storm after the infected cell were treated with let-7b/f mimics." (PMID 35873150, 2022). "In this context, we reported that the viral protein mostly targeted interleukin-6 (IL-6), which represents one of the most important cytokines involved in the so-called cytokine storm occurring during viral infection." (PMID 35746745, 2022). "It is well known that the damage to endothelial cells after viral infection and/or activation of endothelium by pro-inflammatory cytokines, such as IL-1β, IL-6, IFN-γ, IL-8 and TNF-α induces platelets and monocyte aggregation in the vascular wall." (PMID 36291697, 2022). "This symptom is likely to be very intense due to the increase in pro-inflammatory cytokines such as IL-6 or IFN-α which are stimulated as a result of viral infection." (PMID 35389992, 2022). "IL-6 is known to have proinflammatory effects during viral infection, activating multiple immune cell types, including macrophages." (PMID 36128218, 2022). "Researchers have studied IL-6 knock-out mice and found that IL-6 was critical during recovery from viral infections." (PMID 37287491, 2021). "ALI and ARDS are characterized by overproduction of pro-inflammatory cytokines such as IL-1β, TNF-α, and IL-6 as a result of bacterial or viral infection, trauma, excess exposure to oxygen and noxious gases." (PMID 33806560, 2021). "In fact, the proper production of pro-inflammatory markers like IL-6 by various cell types after SARS-CoV-2 infection is positive in resolving the viral infection, that happens as a result of bacterial infections self-limitation due to human immune responses." (PMID 34895167, 2021). "Through our meta-analysis of these transcriptome datasets, 352 genes were suggested to be regulated by IL-6 in different biological conditions, some of which were related to virus infection and cardiovascular disease." (PMID 33520118, 2021). "In general, when a clinically detectable viral infection is present, elevated concentrations of cytokines, including IL-6, IL-1, IL-8, and TNF-α in amniotic fluid or cervicovaginal lavage of patients, is predictive of the onset of preterm labour." (PMID 34835071, 2021). "This is based on the fact that pro-inflammatory cytokines such as IL-6 and TNF-α are released at high levels in response to viral infection and hence predisposed the occurrence of the disorder." (PMID 33802042, 2021). "Whereas many studies reported on the fundamental function of IL-6 to elicit immune response to viral challenges, a relationship between IL-6 and worsening of viral disease has been noted in particular conditions." (PMID 34438732, 2021). "On the other hand, although the viral infection itself triggers lymphocyte response predominantly, the systemic inflammation especially high Interleukin 6 paradoxically decreases the lymphocyte count and resultant cellular immunity." (PMID 34475926, 2021). "Among them, ICAM1 (a well-known gene involved in viral infection and cardiovascular disease) expression has been demonstrated to be consistent with IL-6 expression in mouse macrophages." (PMID 33520118, 2021).
viral infection (continued). "Recent studies showed that MCs are key effector cells of the innate immune system, and during viral infections they release several inflammatory mediators and cytokines, including histamine and IL-6." (PMID 34359931, 2021). "Fibrinogen production by the liver is upregulated in response to cytokines such as IL-6, and released during sterile inflammation or following bacterial or viral infections." (PMID 33439360, 2021). "Single-cell RNA sequencing of infected cells showed that genes induced by virus infections were broadly upregulated, whereas interferon beta/lambda genes, a pro-inflammatory cytokines such as IL-6, were expressed only in small subsets of infected cells." (PMID 33585804, 2021). "IL6, a pro-inflammatory cytokine, plays a crucial role in inflammatory responses, autoimmune diseases, and viral infections." (PMID 34931923, 2021). "IL-18 is an important cytokine produced by macrophages in the early stages of viral infections and subsequently stimulates the production of IL-6 and IFN-γ, which are considered essential for optimal viral host defense." (PMID 34073872, 2021). "IL-6 is a highly inducible pro-inflammatory cytokine secreted by several cell types including monocytes, lymphocytes, fibroblasts and endothelial cells; interleukin-1β (IL-1β) and TNF-α, viral infection and Angiotensin II are able to induce IL-6." (PMID 34001199, 2021). "The expression of genes related to these pathways, such as TNF-α, IL-6 and IL-8, was altered during viral infection." (PMID 34887856, 2021). "In our model of experimental exacerbation, the systemic levels of IL-6 (serum samples) increased significantly on day twelve of assay in response to viral infection compared to the control Air group." (PMID 34203121, 2021). "The inflammatory role of IL-6 and IL-1β in viral infections such as respiratory syncytial virus (RSV) and adenovirus has been reported to influence the susceptibility and severity of the respiratory disease." (PMID 33522421, 2021). "These elements are activated by IL-6 and have immunomodulatory functions in cancer and viral infections." (PMID 33361110, 2021). "Tα1 was shown to promote DCs to secrete inflammatory cytokines, such as TNF-α, IL-6, and IL-8, in response to viral infection." (PMID 34408744, 2021). "It had been reported that cytokine storm is triggered through activation of NF-κB via pro-inflammatory genes (IL-6/STATs) activated in the presence of viral infection." (PMID 34722003, 2021). "One subject, who was found to have had a concurrent systemic viral infection, had an increase in IL-1β, IL-6, IL-10, and TNF-α following chDAB4 incubation which appeared to be inversely proportion to chDAB4 concentration used." (PMID 34231102, 2021). "IL-6, as a pro-inflammatory cytokine, is involved in inflammation and can adversely affect immune responses against virus infection." (PMID 34895167, 2021). "Virus infection induced a robust increase of IL-6, CXCL8, TNF-α, CXCL10, COX-2, and RANTES in mRNA level with a dose-dependent manner." (PMID 34552653, 2021). "Specific inflammatory cytokines such as TNF-α, IL-1β, and IL-6 are permanently induced in obese people; thus, viral infection merely boosts the signal for a cytokine response in already primed adipose tissue." (PMID 35062229, 2021). "For example, it is well-known that IL-6 secreted by immune and endothelial cells in response to a viral infection plays an important role in activating the endothelium during the early phase of inflammation." (PMID 34977191, 2021). "Both the acute HIV-1- and SARS-CoV-2-infected patients showed signs of inflammation, namely elevated C reactive protein (CRP) and ferritin levels, as expected in an acute viral infection, though IL-6 was only elevated in SARS-CoV-2-infected patients." (PMID 34578386, 2021).
viral infection (continued). "Although the IL-1β response module was modestly induced by SARS-CoV-2 infection, the IL-6 response module was significantly enriched in transcriptional programs induced by this viral infection." (PMID 33319166, 2021). "CRP is an acute phase protein released in hepatocytes after stimulation of IL-6 and IL-8 in response to acute inflammation, including viral infections, localized bacterial, and other inflammatory processes, and is involved in different immune functions." (PMID 33713309, 2021). "For viral infection, IL-6 signal is very important to control virus expansion by stimulating CD4+ T cells, leading to germinal center activation and improving antibody response in mice." (PMID 34738866, 2021). "IL-6 gene transcription is induced in normal tissues in response to stimuli including viral infection, bacterial endotoxin, lipopolysaccharide, as well as inflammatory cytokines and IFNs." (PMID 33550983, 2021). "Type 1, Type 17 and pro-inflammatory cytokines (including IL-6, IL-1 and IL-12) are known to play an important role in host immunity to viral infections." (PMID 34721425, 2021). "IL-6 is a multi-functional cytokine that plays roles not only in viral defense but also in the pathogenesis of viral diseases." (PMID 33923020, 2021). "IL6, as a pro-inflammatory mediator, was reported to prominently increase in hepatic inflammation, viral infection, and HCC." (PMID 34714420, 2021). "With the recent COVID-19 pandemic, researchers have been exploring the role that cytokine storms play in the viral infection and in particular, the role of interleukin-6 (IL-6)." (PMID 34562980, 2021). "The combination of Cs and viral infection, in our model, increased serum IL-6 levels while it also reduced mice’s survival when compared to those that were only infected." (PMID 34203121, 2021). "The role IL-6 plays during viral clearance has been shown to favor viral infections in mice infected with Theiler’s murine encephalomyelitis virus." (PMID 35087503, 2021). "Several studies reported the significant role of IL-6 in the progression or suppression of viral infections." (PMID 34895167, 2021). "The production of IFN-I and -III promotes intracellular antiviral defense and the production and release of microglia and macrophage-dependent IL-1β and IL-6, are the primary response to viral infection." (PMID 34484241, 2021). "Grape pomace extracts containing polyphenols interfere with nuclear protein expression, reduce viral replication, relieve the pathological complications of viral infection at the respiratory level, and regulate inflammation-promoting IL-6 in the airway mucosa." (PMID 34067427, 2021). "The role of interleukin 6 (IL-6) in controlling viral infections has been proven in influenza A, herpesvirus, and SARS-CoV-1 infections." (PMID 34205217, 2021). "This broadens its application range even more—for the treatment of viral infections leading to acute inflammatory conditions characterised by increased cytokine levels, in particular those of IL-6 and IFNγ." (PMID 34639073, 2021). "The severity of these viral infections were positively correlated with the levels of IL-17 and other T-helpers 17 cell-related proinflammatory cytokines, such as IL-1, IL-6, IL-15, TNF, and IFN-γ." (PMID 33802042, 2021). "The three immune factors modulated by the EPS of S. thermophilus ST538, IFN-β, IL-6, and CXCL10, have been associated to the protection against viral infections." (PMID 32508770, 2020). "High IFN-γ expression in the context of viral infection negates IL-6 anti-inflammatory effects via inhibiting STAT3-dependent IL-6 signaling." (PMID 33414779, 2020). "This is based on the fact that, in the presence of an exacerbated inflammatory response to viral infection, pro-inflammatory cytokines, such as interleukin-6 (IL6) and tumor necrosis factor alpha (TNF-α), are released at high levels." (PMID 33233769, 2020).
viral infection (continued). "The present study was designed to elucidate the association between CF mt-DNA, IL-6 and viral load in HIV, HBV and HCV infections and predict its role as a potential biomarker to assess the disease severity in viral infections." (PMID 32704253, 2020). "Numerous cytokines are released upon virus infection including IFNs and IL-6, which then stimulate the expression of genes that are involved in anti-viral response via direct or indirect mechanisms." (PMID 32046095, 2020). "Viral infection induced EMT induces secretion of IL6, TGFβ, and other growth factors that trigger expansion of subepithelial myofibroblasts." (PMID 32722537, 2020). "The loss of CaV3.2 initially led to reduced pain transmission in infected neurons; however, the release of interleukin-6 (IL-6) in response to viral infection was subsequently shown to restore CaV3.2 current density and pain responses." (PMID 32756358, 2020). "One prominent Severe Acute Respiratory Syndrome-Coronavirus (SARS-CoV) study found that highly-polarised human bronchial epithelial Calu-3 cells responded to the viral infection by secreting IL-6, IL-8 and gamma interferon (IFN-γ)-inducible protein 10 (IP-10)." (PMID 32788852, 2020). "Clinical studies also show exacerbation of outcomes involving viral infection in humans and animals, linking the increased systemic levels of IL-6 with the chronic occurrence of influenza and several other viruses." (PMID 32788852, 2020). "Interleukin-6 is a proinflammatory and multifunctional cytokine, which plays an important role in the immune response, haematopoiesis and defence against viral infection." (PMID 32266003, 2020). "Further, the overproduction of IL-6 plays a role in the reduced activity of NK cells in mimicked viral infection in vivo." (PMID 33382687, 2020). "Macrophages are key producers of cytokines including IL-6 and other inflammatory mediators in response to viral infections that induce “cytokine storm” and systemic inflammatory reactions." (PMID 32722596, 2020). "Cytokines such as interleukin (IL)‐6 and IL‐8 induced by SARS viral infections have been implicated as playing a critical role in AKI." (PMID 32725744, 2020). "The inhibition of IL-1 family members and of IL-6 is used as a therapeutic strategy in many inflammatory diseases, including viral infections." (PMID 32973818, 2020). "Chloroquine is also immunomodulatory, capable of suppressing the production and release of factors which mediate the inflammatory complications of viral diseases (tumor necrosis factor and interleukin 6)." (PMID 32110875, 2020). "A better understanding of the role of IL-6 under physiological as well as pathological conditions and the preparation of new strategies for the therapeutic control of the IL-6 axis may help to manage the problems associated with the elderly, cancer, and serious viral infections." (PMID 33114676, 2020). "Several papers have described the essential role of IL-6 in generating a proper immune response during different kinds of viral infection in the pulmonary tract." (PMID 32354030, 2020). "CRP is an acute phase protein synthesized by the liver in response to IL-6 increase, which is used as a biomarker of inflammation and to distinguish between bacterial and viral infections." (PMID 32256905, 2020). "Serum levels of interleukin-6, interleukin-8, tumor necrosis factor-α, interferon gamma, and granulocyte colony stimulating factor increase following viral infection." (PMID 33425271, 2020). "The main cells producing IL-6 in brain tissue are astrocytes and microglia, which can be induced to produce IL-6 by stimulation and virus infection." (PMID 32194375, 2020). "IL‐6 long‐term persistence can lead to chronic inflammation and carcinogenesis; however, IL‐6 is also critical to control bacterial, parasitic and viral infection in the liver, such as HBV infection." (PMID 32176810, 2020).